TNF (tumor necrosis factor)
Diseases named in the same sentence as TNF in open-access papers (continued):
Sharing a sentence is not in itself a finding about the gene and the disease.
COVID-19 (continued). "Intraperitoneal administration of CML in zebrafish resulted in acute paralysis, impaired swimming ability, and a sharp increase in neutrophil infiltration, IL-6, and TNF-α levels, resembling the cytokine storm observed in COVID-19 patients." (PMID 39334708, 2024). "On the other hand, we observed a clear pattern of lower production capacity of TNF-α and IL-1β after COVID-19 vaccination, while the release of IL-1Ra was increased in response to almost all stimuli." (PMID 39744634, 2024). "TNF-α blockade is the potential strategy to reduce excessive cytokine release in COVID-19 individuals." (PMID 37742314, 2024). "Patients who tested positive for COVID-19 had elevated CD142 activity, associated with high blood TNF-α levels." (PMID 38291452, 2024). "Our research group has demonstrated that hDPSCs can modulated the production of cytokines such as TNFα, IFNγ, IL-10 and IL-17A by peripheral blood mononuclear cells (PBMCs) obtained from Coronavirus disease 2019 (COVID-19) patients." (PMID 39450172, 2024). "Given the well-established anti-inflammatory properties of curcuminoids, we further explored their role in modulating cytokines, including IL-6, IL-17, IFN-γ, and TNF-α, which are often elevated in COVID-19." (PMID 38730068, 2024). "Being anti-inflammatory in nature, Yashada bhasma fights COVID-19 by reducing plasma interleukins, interferons, and TNFα levels." (PMID 39791040, 2024). "Clinical benefits were also observed in outcomes related to inflammation, such as C-reactive protein and TNF-alpha, in COVID-19 patients (critically low quality)." (PMID 39360254, 2024). "In severe cases of COVID-19, a distinctive cytokine profile emerges, characterized by elevated levels of cytokines and acute-phase reactants such as IL-6, tumor necrosis factor-alpha (TNFα), and ferritin." (PMID 39339673, 2024). "In a Syrian hamster model with SARS-CoV-2 GFP/ΔN, the HSP90 inhibitor 17-DMAG significantly reduced COVID-19 lung injury and gene expression of TNF, IL1B and IL6, but clinical deterioration was observed (weight loss exceeding 20% body weight and ruffled fur)." (PMID 39325762, 2024). "Our study demonstrated that the expression of TNF in the leucocytes was higher in the severe COVID-19 cases compared to the mild cases." (PMID 38187222, 2024). "Modulating the immune responses by intervening at the NF-κB activation and IκB degradation levels coupled with TNF-α inhibition can reduce cytokine storm and mitigate the severity of COVID-19." (PMID 38392902, 2024). "Among the various proinflammatory cytokines identified in individuals with COVID-19, TNF-α and IL-6 are present at higher levels compared to other cytokines." (PMID 39518964, 2024). "At the pandemic’s beginning, elevated cytokine levels (notably IL-6, GM-CSF, TNF, interferons, and IL-18) were commonly reported in severely ill patients with COVID-19, contributing to the cytokine storm." (PMID 39729489, 2024). "Being TNF-α as a core node, it becomes the factor for linking diseases such as chronic inflammatory disorders, including COVID-19, and also interaction with other genes to develop severe conditions." (PMID 38213956, 2024). "The cytokine profile of COVID-19 is characterized by elevated levels of pro-inflammatory cytokines, such as IL-6, TNF-α, IL-1β, and IFN-γ." (PMID 39130641, 2024). "In the context of COVID-19, the cytokine storm involves key cytokines such as tumor necrosis factor-alpha (TNF-α), interleukin 6 (IL-6), and interleukin 1 (IL-1)." (PMID 39429337, 2024). "The seven pro-inflammatory cytokines (IL-6, IL-8, IL-15, IL-18, IL-27, IFN-γ, and TNF-α) and two anti-inflammatory cytokines (IL-1RA and IL-10) were elevated in COVID-19 patients compared to healthy controls." (PMID 39408907, 2024). "TNF has been identified as a core gene target in Lithospermum erythrorhizon against COVID-19, and Tormentic acid, a primary component of Lithospermum erythrorhizon, has shown strong binding affinity with TNF68." (PMID 38834599, 2024).
COVID-19 (continued). "In this study, we investigated the associations of the TNF -308G/A and IFNG +874T/A polymorphisms with COVID-19." (PMID 38675991, 2024). "In this sense, a systematic study showed that treatment with MT in a dosage of 5–25 mg/day favored a decrease in the inflammatory markers including IL-6, CRP, and TNF-α in the plasma of COVID-19 patients." (PMID 38674128, 2024). "The findings from this investigation unveiled heightened plasma levels of key proinflammatory cytokines, including interleukin IL-1β, IL-6, TNF-α, monocyte chemoattractant protein-1, and soluble intercellular adhesion molecule-1 in COVID-19 patients." (PMID 38448675, 2024). "The high levels of TNF in severe COVID-19 are likely because of the activation of induced cell death and/or the redistribution of cells in tissue fields." (PMID 38187222, 2024). "In the severe COVID-19 group, levels of autoantibodies against IL-1α, IFNα2, TNFα, osteopontin and IFNβ all showed high correlation." (PMID 38491326, 2024). "Patients with severe COVID-19 present with increased levels of TNF and IFN-γ, which can drive PANoptosis." (PMID 39205235, 2024). "Investigations show that the levels of tumor necrosis alpha (TNFα) and Interleukin (IL-6) are high in patients with COVID-19 And in severe cases of COVID-19, the production of IL-6 and TNF-α and other cytokines is profoundly increased." (PMID 39118801, 2024). "Further, SLE and COVID-19 can interact via IFN-I/II and IFN-I/II receptors, promoting the levels of monokines, including interleukin (IL)-6/10, tumor necrosis factor-α, and IFN-γ, and elevating the incidence rate and risk of cytokine release syndrome." (PMID 38862942, 2024). "The excessive production of pro-inflammatory cytokines, such as IL-6, TNF-α, and IL-1β, leads to a cytokine storm, which is a key driver of the severe manifestations of COVID-19." (PMID 39130641, 2024). "Specifically, in the context of COVID-19, a robust inflammatory response is present, as evidenced by elevated levels of IL-1 beta, IL-6, and TNF-alpha." (PMID 39511501, 2024). "TNFα and IL-6 serve as well-established druggable cellular targets with several FDA-approved anti-TNFα or IL-6 drugs either suggested for COVID-19 treatment or in various clinical trials." (PMID 38251382, 2024). "IL-6 and TNF-α have been confirmed to be critical cytokines in the pathogenesis of COVID-19, and their levels are correlated with the severity and prognosis of COVID-19." (PMID 39650159, 2024). "This study showed a considerable rise in TNF-α and IL-1β serum levels exclusively in COVID-19 patients with TT rs2070788 TMPRSS2 SNP genotype compared to healthy controls." (PMID 39188881, 2024). "Another study also showed than attenuated sFasL resulted in TNF-driven neutrophil necroptosis in critical COVID-19 patients." (PMID 38803919, 2024). "Most of the aminopyridine N-oxide family members exhibited inhibition of both MAPK and TNF-α, indicating their potential therapeutic relevance for COVID-19." (PMID 39130417, 2024). "Among the pro-inflammatory cytokines observed in COVID-19 patients, interleukin-6 (IL-6), interleukin-1-beta (IL-1β), interferon-gamma (IFN-γ) and tumor necrosis factor-alpha (TNF-α) are generally associated with illness progression." (PMID 39199315, 2024). "In acute COVID-19, TNF-α, IFN-α, STING and cGAS showed a performance that varied from fair to good in differentiating severe and non-severe cases, with area under the curve (AUC) ranging from 0.7051 to 0.8145 (p < 0.05)." (PMID 38424312, 2024). "PBMCs isolated from COVID-19 patients (n = 56) showed significant upregulation of IL-1ß mRNA and TNF-α mRNA in comparison to the control group (p < 0.0001)." (PMID 38183501, 2024). "A study has found that inflammatory factors including IL-2, YKL40, IL-4, IL-6, IL-10, sCD40L, TNF-α, IL-1Ra, interferon-gamma (IFN-γ), and CRP, are associated with cognitive impairment in COVID-19 patients." (PMID 38012459, 2024).
COVID-19 (continued). "It has also been reported that the constitutive activation of NF-κB and enhanced TNFα, IL-1β, and IL-6 levels is a ubiquitous phenomenon among various cell types in severe COVID-19 patients." (PMID 37872376, 2024). "Among COVID-19 patients, the median TNF-α level is 160 pg/mL, with an IQR, excluding outliers, spanning from about 154.00 to 165.00." (PMID 39201618, 2024). "Potential associations within COVID-19 group between heteroplasmic variant burden, along with the averaged REA values, and inflammatory mediators such as IL-6, IFN-α, TNF-α, and IL-10 were analyzed by Spearman rank correlation analysis." (PMID 38377022, 2024). "Furthermore, alterations in the oral microbiome have been seen in COVID-19 patients including a reduced diversity, especially in older patients, and bacteria associated with periodontal disease have been shown to stimulate IL-6 and TNF-α production by immune cells." (PMID 39345212, 2024). "Several studies have reported an increase in the systemic levels of pro-inflammatory mediators such as TNF-α, along with components of the interleukin family, among patients with COVID-19 requiring intensive care unit (ICU) admission." (PMID 38474248, 2024). "Treatments aimed at reducing COVID-19 symptoms in hospitalized patients, such as corticosteroids or specific TNF-α antagonists like infliximab, have been shown to reduce TNF-α." (PMID 39199439, 2024). "Infliximab, a tumor necrosis factor inhibitor, has been reported to improve outcomes in COVID-19 patients by targeting the hyperinflammatory response." (PMID 39459457, 2024). "The so-called cytokine storm in severe COVID-19 is mediated by an exponential increase in the levels of inflammatory cytokines such as interleukin-6 (IL-6) and tumor necrosis factor-alpha (TNF-α)." (PMID 38384612, 2024). "Gene analysis suggests that resveratrol targets the IL-17, NF-κB, and TNF signaling pathways in COVID-19 therapy." (PMID 39126050, 2024). "Some studies have proposed to consider the potential therapeutic role of TNF inhibitors for COVID-19." (PMID 39130417, 2024). "The biology of TNF-α has properties that make it a promising target for treatment in patients with COVID-19." (PMID 39118801, 2024). "The main inflammatory cytokines and chemokines widely produced by patients with severe forms of COVID-19 are IL-6, IL-8, IL-1β, TNF-alpha, IFN-gamma, MIP1α and 1β, CCL2, CCL5, CCL20, CXCL1, CXCL2, CXCL8, CXCL10, and CXCL17." (PMID 39768136, 2024). "This synergy between drug and cytokine storm triggered by COVID-19, mainly TNF α, IFN-gamma, LT CD 8+, and Th17 deregulation, can induce a hypersensitivity reaction to the drugs involving toxidermia." (PMID 38707102, 2024). "Most of the research focused attention on the first COVID-19 wave, in which high concentrations of IL-1β, tumor necrosis factor (TNF)-α, IL-6, IL-10, and interferon γ-induced protein (IP)-10 were observed in patients with severe forms of COVID-19." (PMID 39194742, 2024). "In our study, we found a dysregulation of cytokines such as IL-1RA, TNF-α, IP-10, and PDGFb, which are elevated in combination in the plasma of COVID-19 patients in other studies and correlate with disease severity." (PMID 38791465, 2024). "IL-10, IL-6, MIP-1α, MCP-1, MCP-3, and TNF-α were significantly elevated in critical COVID-19 (OS7) compared to moderate COVID-19." (PMID 39494457, 2024). "The COVID-19 EVs group had increased levels of IL-1β, IL-6, and TNF-α compared to the other two groups." (PMID 39475319, 2024). "Of the 105 cytokines profiled in this study, nine were previously reported to be involved in the cytokine storm associated with COVID-19 including the following: IL-2, IL-4, IL-6, IL-10, G-CSF, IP-10, MCP-1, TNF-α, and IFN-γ." (PMID 39062978, 2024). "The relationship between the expression of miR-9, the transcription factor NF-κB, and the pro-inflammatory cytokines IL-6, IL-1β, and TNF-α in a cohort of COVID-19 patients was investigated." (PMID 39201618, 2024).
COVID-19 (continued). "Plasma levels of IL-2, IL-7, IL-10, granulocyte colony-stimulating factor (G-CSF), IP-10, MCP1, macrophage inflammatory protein 1α (MIP1α), and tumor necrosis factor (TNF) have been observed in patients with severe COVID-19 were higher than in healthy adults." (PMID 38648205, 2024). "COVID-19 has been associated with the excessive production of proinflammatory cytokines, such as IL-6, IFN γ, and TNF-α." (PMID 39407725, 2024). "The gene expression of the core pro-inflammatory cytokines in COVID-19, IL-6, and TNFα, were significantly lower with OmeGo than in the BSC group (p < 0.01)." (PMID 39000027, 2024). "In accordance, the results of the present study showed upregulation of both TNF-α and IL-1β cytokines in COVID-19 patients compared to control subjects." (PMID 38183501, 2024). "ORF3a-mediated signaling pathways involve key cellular regulators such as NLRP3, NF-κB, and related cytokines (TNFα and IL-6), all well-known druggable cellular targets relevant to COVID-19." (PMID 38251382, 2024). "In our study, a significant increase in IL-1β and TNF-α serum levels was exclusively observed in carriers of the TT genotype of the rs2070788 TMPRSS2 SNP in COVID-19 patients compared to healthy controls." (PMID 39188881, 2024). "For instance, three FDA-approved TNFα inhibitor drugs (infliximab, adalimumab, and etanercept) have displayed encouraging clinical outcomes in managing COVID-19." (PMID 38251382, 2024). "ER suppresses the transcription of several proinflammatory markers, such as TNF-α, IL-1β, and IL-12, suggesting its potential in regulating cytokine storms and consequently managing COVID-19." (PMID 39459194, 2024). "These included the Coronavirus disease-COVID-19, the TNF signaling pathway, the JAK-STAT signaling pathway, the NF-kappa B signaling pathway, and the RIG-I-like receptor signaling pathway." (PMID 39147857, 2024). "We also confirmed our previous finding that patients on anti-TNF therapy have an augmented CMIR to mRNA COVID-19 vaccines." (PMID 38349178, 2024). "Our data reveal that the endothelial cells that are in contact with COVID-19 serum, are exposed to the cytokine TNF-α that is in the systemic circulation of COVID-19 patients." (PMID 38771750, 2024). "IL-8, D-dimer, S100B, IL-6, Angpt-2, MMP-8, TNF-R1, u-PAR, u-PA, osteopontin, IL-13, TNF-α, pentraxin-3, P-selectin, fractalkine, and SP-D levels were elevated in critically ill COVID-19 males compared to severe cases." (PMID 39507250, 2024). "For instance, genotyping of cytokine-related single-nucleotide polymorphisms (SNPs), e.g., IL-6 rs1800796, IL-10 rs1800896, TNF-α rs1800629, and IFITM3 rs12252, has shown them to underlie the differential viral virulence and severity of COVID-19." (PMID 38400050, 2024). "As markers of immune response were elevated in COVID-19-infected mice and exposed patients, we also assessed hippocampal mRNA levels of tumor necrosis factor (TNF)-α, interleukin (IL)-4, interferon (IFN)-γ, and C-C motif chemokine 11 (CCL11 or Eotaxin)." (PMID 39660133, 2024). "TNF-α levels also showed a significant increase, with healthy individuals having a mean of 54.53 ± 17.93 pg/mL and COVID-19 patients showing levels of 91.87 ± 13.83 pg/mL (p < 0.001)." (PMID 39407725, 2024). "Unlike for CD8+ T cells, higher frequencies of multifunctional CCCs/SARS-CoV-2-cross-reactive memory CD4+ T cells, expressing CD69, CD107a/b, and TNF-α were detected in COVID-19 patients compared to healthy individuals." (PMID 38605956, 2024). "TNF-α, IL-8 and IL-10 are key cytokines in COVID-19 pathogenesis, and CXCR-2 is a major chemokine receptor involved in inflammatory response." (PMID 38544825, 2024). "Studies have indicated that patients with severe COVID-19 exhibit elevated levels of pro-inflammatory cytokines (IL-6, tumor necrosis factor-α) and anti-inflammatory cytokines (IL-4, IL-10), along with decreased expression of CD4 and CD8 cells." (PMID 39040601, 2024).
COVID-19 (continued). "The persistently high interleukin-6 (IL-6) and tumor necrosis factor-α (TNF-α) levels in severe COVID-19 patients are important products of toll-like receptor 4 (TLR4) signaling." (PMID 38165854, 2024). "A comparative analysis of cytokines in BALF and blood plasma of severe patients with ARDS against the background of COVID-19 showed increases in the levels of TNF-α, IL-1α, IL-1β, IL-1ra, IL-6, IL-10, and IL-33 cytokines relative to healthy donors." (PMID 39457048, 2024). "Critically ill COVID-19 patients exhibit significantly higher concentrations of interleukins, TNF-α, and immune attractant proteins (protein 1 and protein 1A) compared to mildly infected cases." (PMID 38694122, 2024). "Treatment of bone marrow-derived macrophages with COVID-19 EVs enhanced the M1 phenotype and augmented the production of IL-1β, IL-6, and TNF-α." (PMID 39475319, 2024). "Several clinical studies have postulated that cytokines (IL-1, IL-6, IL-8, and TNF-α) and chemokines were abnormally raised to high levels in COVID-19 patients." (PMID 38392902, 2024). "Longitudinal serum cytokine analysis of 207 COVID-19 patients revealed that in early inflammatory responses, IL-6, TNF-α, IL-10, and IL-1β expression increased in those with severe disease." (PMID 38710800, 2024). "Critical COVID-19 patient had significantly higher levels of pro-inflammatory cytokines, in particular IL-1β, IL-6, IL-8, tumor necrosis factor (TNF-α), as well as IFN-γ." (PMID 38803919, 2024). "GSH has also been shown to reduce levels of TNF-α, a proinflammatory cytokine found upregulated in COVID-19 which triggers cytokine release syndrome (CRS) and facilitates SARS-CoV-2 binding with angiotensin-converting enzyme 2 (ACE2)." (PMID 38539805, 2024). "In severe COVID-19, the cytokine storm results from a hyperactive Th1/Th17 immune response, leading to elevated IL-6 and TNF-α." (PMID 40735669, 2024). "Both serum levels of TNF-α and IL-2R are remarkably higher in COVID-19 patients with severe symptoms." (PMID 39538233, 2024). "They suggest that these results indicate a strong involvement of the TNF-α/TNFR1/NF-κB pathway in COVID-19 pathogenesis." (PMID 40008234, 2024). "In contrast, after vaccination against COVID-19, a lower TNF-α and IL-1β production capacity was observed, complemented by higher anti-inflammatory IL-1Ra production capacity." (PMID 39744634, 2024). "Literature has suggested that MAPK and TNF-α are potential therapeutic targets for COVID-19 Another high-scoring compound CHEMBL200004 displayed an inhibitory activity against CTSK in biological detection." (PMID 39130417, 2024). "In COVID-19 cases, a decrease in peripheral lymphocyte numbers occurs due to various factors, such as TNF-alpha-induced apoptosis, increased peripheral consumption, ACE-2-related cytopathic effects, and interaction with CD147." (PMID 39685844, 2024). "Recent discussions have explored the potential preventive benefits of TNF inhibitors in managing severe COVID-19 cases." (PMID 39459457, 2024). "The high expression of tissue factor (also known as CD142) on the surface of vesicles of COVID-19 patients was also found to be biologically active and a reliable prognostic marker correlating with serum levels of TNF-α." (PMID 39697632, 2024). "Convalescent COVID-19 children had elevated levels of IFNγ, IL-2, TNFα, IL-1α, IL-1β, IFNα, IFNβ, IL-6, IL-12, IL-17A and G-CSF in comparison to control children." (PMID 37013538, 2023). "We also found a statistically significant increase in CTSL, AngII and TNFα values in vaccinated individuals compared to both healthy controls and COVID-19 patients." (PMID 38137381, 2023). "KEGG pathway enrichment analysis showed that these genes were largely associated with COVID-19, ribosomes, leukocyte trans endothelial migration, IL17 signaling pathway, TNF signaling route, and apoptosis." (PMID 37728418, 2023).